Y_RNA (Y RNA )
Gene: Miscellaneous RNA gene on chromosome 18 (9,250,110 to 9,250,211, forward strand). Ensembl gene ENSG00000207092.
Homologues: Orthologues: chimpanzee Y_RNA (99% identical), macaque Y_RNA (89% identical). Paralogues in human: Y_RNA (86% identical), Y_RNA (85% identical), RNY3 (84% identical), Y_RNA (84% identical), RNY3P1 (83% identical), Y_RNA (83% identical), Y_RNA (82% identical), RNY3P9 (81% identical), Y_RNA (81% identical), RNY3P14 (80% identical), RNY3P5 (80% identical), Y_RNA (80% identical), and 93 more.